CAP1 (cyclase associated actin cytoskeleton regulatory protein 1)
Diseases named in the same sentence as CAP1 in open-access papers (continued):
Sharing a sentence is not in itself a finding about the gene and the disease.
pancreatic cancer (continued). "CAP1 has been to be commonly overexpressed in pancreatic cancers, and its level in clinical cases has been shown to be associated with neuronal invasion and lymph node metastasis." (PMID 25652936, 2015). "The primary objective of this study was to determine the optimal dose of the carcinoembryonic antigen (CEA) peptide (CAP1-6D)/Montanide/GM-CSF-vaccine amongst the three doses administered to induce a maximal CTL response in patients with pancreatic cancer." (PMID 24829746, 2013). "Moreover, cap1 has been identified as a potential biomarker by the analysis of the pancreatic cancer proteome." (PMID 35237592, 2022). "Interestingly, glycogen synthase kinase 3 (GSK3), which was reported to be hyper-activated in pancreatic cancer, can phosphorylate CAP1." (PMID 33072768, 2020). "Interestingly, we found that growth factor PDGF induced CAP1 dephosphorylation at S308/S310 in both PANC-1 and AsPC-1 cancer cells, suggesting a likely role for CAP1 in mediating extracellular signals to control the invasiveness of pancreatic cancer cells." (PMID 30894654, 2019). "Such novel mechanistic insights may ultimately lead to the development of strategies targeting CAP1 or its regulatory cell signals for improving the treatment outcome of pancreatic cancer." (PMID 30894654, 2019). "We next attempted to silence CAP1 to determine the roles of CAP1 in pancreatic cancer cells." (PMID 30894654, 2019). "Depletion of CAP1 in pancreatic cancer cells also led to reduced FAK activity but did not cause considerable alterations in ERK, which are consistent with that no significant alterations in proliferation of pancreatic cancer cells was detected." (PMID 30894654, 2019). "The other cancer types, including pancreatic cancer, only had low to medium CAP1 expression." (PMID 30894654, 2019). "A previous study suggested that up-regulated CAP1 promotes pancreatic cancer cell motility." (PMID 30894654, 2019). "CAP1 protein levels were determined in Western blotting in a panel of commonly used pancreatic cancer cell lines {PANC-126, CFPAC-127, AsPC-128 and Mia PaCa-229}, and compared to that in the immortalized but untransformed pancreas cell line hTERT-HPNE30, which serves as a control." (PMID 30894654, 2019). "Moreover, we identify a crucial role for S308/S310 phosphorylation for CAP1 functions in regulating the actin cytoskeleton and invasiveness of pancreatic cancer cells." (PMID 30894654, 2019). "Knockdown of CAP1 leads to reduced cell motility in lung and pancreatic cancer." (PMID 28423713, 2017). "CAP1 phosphorylation is elevated in cancer cells, consistent with the reported hyper-activation of GSK3 in pancreatic cancer." (PMID 30894654, 2019). "Phosphorylation of CAP1 at the S308/S310 tandem regulatory site was elevated in cancer cells, consistent with hyper-activated GSK3 reported in pancreatic cancer." (PMID 30894654, 2019). "Our current study identified the change of exosome and lipid metabolism-related genes with clinical value, and the 7-gene (ABCB1, CAP1, EGFR, ITGB1, MAPK1, PPARG, SNCA) prognostic formula is a novel and reliable predictive index in pancreatic cancer and other multiple cancers." (PMID 37857015, 2023). "Additionally, the mRNA level of CAP1, EGFR and PPARG were identified with significant downregulation in pancreatic cancer cell lines compared to normal pancreatic cells." (PMID 37857015, 2023). "Disrupting CAP1 phospho-regulation via GSK3 inhibition or expressing phospho-site mutants compromised CAP1 functions in alleviating enhanced stress fibers and in rescuing invasiveness of CAP1-knockdown pancreatic cancer cells." (PMID 33072768, 2020). "In another study, no changes in CAP1 expression in pancreatic cancer lines have been reported, but an increase in CAP1 phosphorylation at serine residues S308/S310 has been detected." (PMID 33072768, 2020). "At least a sub-population of cancer cells in pancreatic cancer tissues had no or marginal CAP1 staining." (PMID 30894654, 2019).
pancreatic cancer (continued). "We did not detect up-regulation of CAP1 in any of the four pancreatic cancer cell lines tested, by directly comparing the expression levels to that in the immortalized but untransformed hTERT-HPNE pancreas cells." (PMID 30894654, 2019). "Treatment of pancreatic cancer cells with HGF or serum did not have a considerable effect in inducing the dephosphorylation of CAP1 (shown for PANC-1 cells)." (PMID 30894654, 2019). "The elevated CAP1 phosphorylation in pancreatic cancer cells, consistent with the activated GSK3, suggests that phosphor-regulation may also play a role for CAP1 function in cancer cell invasiveness." (PMID 30894654, 2019). "Our results, including from the MTT proliferation assays, support that CAP1 does not play a significant role in regulating the proliferation of pancreatic cancer cells." (PMID 30894654, 2019). "We tested if CAP1 may also regulate ERK and proliferation in pancreatic cancer cells." (PMID 30894654, 2019).
Insulin resistance (6 papers, 2019 to 2025). Increased resistance towards insulin, that is, diminished effectiveness of insulin in reducing blood glucose levels. "Using BNL CL.2 cells, we investigated the effect of resistin in untransfected or CAP1 siRNA-transfected cells on the expression of 84 key genes involved in insulin resistance." (PMID 31294061, 2019). "•We found that resistin modulates gene expression of several genes related to insulin resistance, and the effect of some of these genes is modulated by CAP1." (PMID 31294061, 2019). "Interestingly, LUZP6 RNA is enriched in salivary exosomes and, together with another three genes (IL1R2, VPS4B and CAP1) comprising an RNA signature, could distinguish high from low insulin resistance as an extracellular RNA marker." (PMID 34073722, 2021).
lung carcinoma (6 papers, 2017 to 2023). "Cyclase associated protein 1 (CAP1) is associated with lung cancer and post-translational modification promotes proliferation and migration." (PMID 37005656, 2023). "Overexpression of CAP1 has further been linked to poor prognosis in other types of cancer including lung cancer, hepatocellular carcinoma, and epithelial ovarian cancer." (PMID 32560703, 2020). "Both in vitro and in vivo experiments showed that S308/S310 phosphorylation in CAP1 facilitated proliferation and metastasis of lung cancer cells." (PMID 34636991, 2022). "Our previous study showed that the expression of CAP1 differs in different metastatic lung cancer tissues, which indicates that CAP1 is a cancer-related protein." (PMID 34636991, 2022). "TCGA database from GEPIA was used to validate the OS between CAP1 mRNA expression levels in lung cancer patients and the data revealed that lung cancer patients with higher CAP1 mRNA expression level corresponded to a worse prognosis." (PMID 34636991, 2022). "From our research, we collected 78 lung cancer serum samples; among them, 30 are EGFR mutation samples; it is hard to explore the relationship between EGFR mutation and CAP1 expression with limited sample size." (PMID 34636991, 2022). "We applied extensive bioinformatics analysis to determine CAP1’s role in different cancers and especially in lung cancer." (PMID 34636991, 2022). "To investigate the role of CAP1 in lung cancer cells, we transfected A549 cell line with lentivirus to stably knock down CAP1." (PMID 34636991, 2022). "Protein CAP1 phosphorylation rate was higher in lung cancer tissue compared with normal tissue and had a direct correlation to the disease stage and grade." (PMID 34636991, 2022). "Lung cancer H1975 cells were used to validate the result that CAP1 depletion inhibited proliferation and motility." (PMID 34636991, 2022). "Massive bioinformatics analysis was applied to determine CAP1’s role in different cancers and especially in lung cancer." (PMID 34636991, 2022). "Higher serum CAP1 protein level correlated with poor prognosis, and higher pCAP1 and CAP1 protein levels were observed in lung cancer patients’ tumor tissue compared with adjacent normal tissue." (PMID 34636991, 2022). "CAP1 showed a higher phosphorylation rate in lung cancer, and the phosphorylation rate had a direct correlation to the stage and grade of lung cancer." (PMID 34636991, 2022). "These outcomes strongly indicated that the phosphorylation of CAP1 plays a prominent role in tumor development and acceleration of lung cancer metastasis." (PMID 34636991, 2022). "Both in vitro and in vivo experiments were performed to investigate the roles of CAP1 phosphorylation and de-phosphorylation in lung cancer A549 cells." (PMID 34636991, 2022). "Taken together, our research showed that CAP1 was overexpressed in most cancers, including lung cancer." (PMID 34636991, 2022). "The purpose of our study was to observe the role of CAP1 in lung cancer and its PTM on lung cancer cells’ proliferation and metastasis." (PMID 34636991, 2022). "Our previous study confirmed the role of CAP1 in lung cancer demonstrated that the expression of CAP1 was significantly higher in NSCLC tissues as compared to the corresponding normal lung tissues." (PMID 28423713, 2017). "Kaplan-Meier plotter analysis showed the relationship between the overexpression of CAP1 and overall high survival rates in lung cancer." (PMID 28423713, 2017). "CAP1 has been reported with upregulation in multiple gastrointestinal, breast, and lung cancers." (PMID 37857015, 2023). "In the present study, we aimed to investigate the role of CAP1 phosphorylation in lung cancer." (PMID 34636991, 2022). "Additionally, we investigated the role of CAP1 phosphorylation in lung cancer A549 cells and validated CAP1’s role in H1975 cells." (PMID 34636991, 2022). "In lung cancer, high CAP1 mRNA level was observed with a shorter OS and DFS." (PMID 34636991, 2022).
lung carcinoma (continued). "In addition, phosphorylated S308 and S310 in CAP1 promoted lung cancer cell proliferation, migration, and metastasis both in vitro and in vivo." (PMID 34636991, 2022). "Phosphorylated S308 and S310 in CAP1 promoted the proliferation and migration of lung cancer cells." (PMID 34636991, 2022). "Overall, these results indicated that phosphorylation CAP1 could induce the migration capabilities of human lung cancer cells through promoting EMT." (PMID 34636991, 2022). "Thus, we verified that CAP1 phosphorylation promotes the development of lung cancer by promoting epithelial–mesenchymal transition, both in vitro and in vivo." (PMID 34636991, 2022). "besides, the Phosphorylation of CAP1 could promote the proliferation, migration and invasion in lung cancer." (PMID 35237592, 2022). "Thus, to evaluate the oncogenic or tumor suppressor role of CAP1 in lung cancer, our previous study demonstrated that the protein expression was significantly higher in NSCLC tissues compared with their matched normal lung tissues." (PMID 28423713, 2017). "Phosphorylation sites of CAP1 might be a novel target for lung cancer treatment." (PMID 34636991, 2022). "In addition, the expression of CAP1 in tumor tissues was significantly associated with a tumor, lymph node metastasis, and TNM stage in NSCLC patients; CAP1 was highly expressed in lung cancer with brain metastasis as compared to other metastatic groups (bone metastasis and visceral metastasis)." (PMID 28423713, 2017). "The DFS between CAP1-high-expression level and low-expression level in lung cancer patients was also compared in TCGA and data revealed that NSCLC patients with high CAP1 expression level gained a shorter DFS time." (PMID 34636991, 2022). "CAP1 high expression correlated with shorter OS in various cancers which includes lung cancer and shorter DFS in lung cancer, as well." (PMID 34636991, 2022). "In addition, we found that phosphorylation of CAP1 promoted EMT, thereby facilitating lung cancer cells’ metastasis." (PMID 34636991, 2022). "The Oncomine, PrognoScan and Kaplan-Meier plotter data showed the oncogenic role of CAP1 in breast, ovarian, blood, and brain cancer; however that in lung cancer is not clear." (PMID 28423713, 2017).
Obesity (6 papers, 2017 to 2021). Accumulation of substantial excess body fat. "Silencing of CAP1 decreased cell proliferation in both T47D and MDA-MB-231 cells, and reduced the obesity-associated secretome-induction of phosphoproteins involved in cell proliferation pathways." (PMID 33738261, 2021). "Adenylate cyclase-associated protein 1 (CAP1), an actin regulatory protein and functional receptor for the obesity-associated adipokine resistin, has been implicated with inferior cancer prognosis." (PMID 32560703, 2020). "The pathobiological role of the resistin-CAP1 axis in obesity-related colorectal carcinogenesis remains largely unknown." (PMID 28422056, 2017). "We hypothesized that the adipocyte secretome, placed under pressure mimicking obese metabolic conditions, would promote cell cycle progression and induce signaling pathways involved in proliferation and motility, and that CAP1 silencing would reduce these obesity-induced changes." (PMID 33738261, 2021).
Sepsis (5 papers, 2024 to 2025). Sepsis is defined as life-threatening organ dysfunction caused by a dysregulated host response to infection. "As a ligand, RETN engages receptors such as TLR4 and CAP1 and activates the NF-κB signaling pathway, which promotes release of large amounts of proinflammatory cytokines and drives the systemic inflammatory response in early sepsis." (PMID 41472734, 2025). "Baseline characteristics were similar in this subset compared with the full Ubon-sepsis CAP cohort and etiologies of bacteremia showed similar separation between CAP1 and CAP2 in this subset." (PMID 41209652, 2025).
atherosclerosis (4 papers, 2017 to 2024). A disease characterized by the build-up of fatty material and calcium deposition in the arterial wall resulting in partial or complete occlusion of the arterial lumen. "rhPCSK9 treatment enhanced oxidized LDL (ox-LDL) uptake in monocytes, leading to foam cell formation, which is another important function of monocytes in atherosclerosis; however, ox-LDL uptake was reduced in CAP1-deficient monocytes." (PMID 38555386, 2024). "Those which were significantly less abundant on treatment included; glyoxalase 1 and adenylyl cyclase-associated protein 1 (CAP1), which have both recently been studied in regards to atherosclerosis and monocyte function, respectively." (PMID 28350877, 2017). "In contrast, PCSK9-induced atherosclerosis was significantly prevented in heterozygous Cap1 knockout mice, suggesting that CAP1 may be a viable target for controlling atherosclerosis." (PMID 38555386, 2024). "Hence, modulation of CAP1 activity may provide a novel therapeutic avenue for atherosclerosis and other cardiovascular diseases." (PMID 33072768, 2020). "As far as concern CAP1 and CAP2, potential roles have been described for various human pathologies apart from the already mentioned contributions of CAP1 to atherosclerosis or other cardiovascular diseases and of CAP2 to heart diseases and 6p22 syndrome." (PMID 33072768, 2020). "Using heterozygous Cap1 knockout mice, we showed that CAP1 could be a therapeutic target that can prevent PCSK9-induced vascular inflammation and atherosclerosis." (PMID 38555386, 2024). "We investigated whether CAP1 was required to induce PCSK9-mediated atherosclerosis using a model of partial ligation of the carotid artery to induce D-flow at the distal end15 under high-fat diet conditions in WT and Cap1+/− mice with or without tail vein injection of AdV-PCSK98." (PMID 38555386, 2024).
hepatocellular carcinoma (4 papers, 2015 to 2021). A malignant tumor that arises from hepatocytes. "Moreover, CAP1 co-localizes with actin in the leading edge of lamellipodia in hepatocellular carcinoma cells." (PMID 33072768, 2020). "CAP1 overexpression in hepatocellular carcinoma specimens correlates with tumor metastasis." (PMID 33072768, 2020). "Western blot analysis, real-time PCR and immunohistochemical analysis have been used to prove that CAP1 is overexpressed in hepatocellular carcinoma compared with adjacent non-cancerous liver tissues, and that it is positively associated with HCC cell metastasis." (PMID 25652936, 2015).
ovarian carcinoma (4 papers, 2017 to 2022). A malignant neoplasm originating from the surface ovarian epithelium. "Although some of the proteins identified in our ubiquitination dataset are known to be associated with ovarian cancer, such as CAP1, CRABP2, EPCAM or KRT8, their ubiquitination status has not been previously investigated in HGSC." (PMID 35292711, 2022). "Another study has reported that CAP1 gene expression increases in other cancers, such as ovarian cancer, and is involved in cell proliferation." (PMID 34290294, 2021). "The poor prognosis in breast and ovarian cancer patients with higher CAP1 expression was in line with the data from Kaplan-Meier plotter analysis." (PMID 28423713, 2017). "Contrastingly, breast and ovarian cancers showed the relationship between overexpression of CAP1 and overall low survival rates." (PMID 28423713, 2017). "Overall, high levels of CAP1 gene expression result in low survival in breast and ovarian cancers." (PMID 28423713, 2017).
coronary artery disease (3 papers, 2018 to 2022). "Subsequent studies have found an association of resistin and CAP1 with conditions like coronary artery disease and rheumatoid arthritis." (PMID 30018317, 2018). "Considering Resistin’s ability to stimulate lipid uptake and atherosclerotic plaque progression, CAP1 and Resistin levels have been assessed in patients affected by coronary artery disease." (PMID 33072768, 2020). "Furthermore, in the aorta, HFD + A treatment significantly downregulated the expression of adenylyl cyclase-associated protein 1 (CAP1), a human resistin receptor that increases the expression of CD36 mRNA, associated with coronary artery disease." (PMID 35268023, 2022). "The results revealed a significant increase in plasma Resistin levels and in CAP1 expression in peripheral blood mononuclear cells of coronary artery disease patients, suggesting that Resistin is able to exert its effects stronger on cells with up-regulated CAP1." (PMID 33072768, 2020).
glioma (3 papers, 2016 to 2020). A benign or malignant brain and spinal cord tumor that arises from glial cells (astrocytes, oligodendrocytes, ependymal cells). "Overexpression of CAP1 may have significant clinical implications as a diagnostic/prognostic factor for lung cancer, esophageal squamous cell carcinoma, epithelial ovarian cancer and glioma." (PMID 33072768, 2020). "Several publications reported altered CAP1 expression in a growing list of human cancers that include glioma, oral squamous cell carcinoma as well as breast, pancreatic, liver, lung and epithelial ovarian cancer." (PMID 33072768, 2020). "For instance, CAP1 has been shown to be overexpressed in pancreatic cancer, esophageal squamous cell carcinoma, lung cancer, hepatocellular carcinoma, epithelial ovarian cancer, breast cancer, and glioma." (PMID 32042970, 2020). "Earlier studies confirmed that CAP1, a homolog of CAP2, is overexpressed in many cancers, and its expression was correlated with tumor grades in human epithelial ovarian cancer and glioma, and with the degree of malignancy in glioma." (PMID 32042970, 2020).